IGF1 (insulin like growth factor 1)
Diseases named in the same sentence as IGF1 in open-access papers (continued):
Sharing a sentence is not in itself a finding about the gene and the disease.
microcephaly (35 papers, 2012 to 2025). A congenital or acquired developmental disorder in which the circumference of the head is smaller than normal for the person's age and sex. "Rare human cases of IGF-1 deficiency are characterized by growth alteration, microcephaly, sensorineural deafness, and delayed psychomotor development." (PMID 38247874, 2024). "In mice, the deficiency of Igf1 and its receptor often leads to postnatal lethality, and mice that do survive to adulthood show microcephaly associated with increased neuronal death and the impairment of myelination." (PMID 38247874, 2024). "Insulin-like growth factor 1 (IGF-1) is a peptide hormone essential for the proper development and growth of the organism, as a complete knockout of Igf1 in mice is lethal, causing microcephaly, growth retardation and the defective development of organs." (PMID 38247874, 2024). "Deficiency of IGF-1 in humans leads to issues such as microcephaly, mental retardation, deafness, and postnatal growth failure." (PMID 38300646, 2024). "The importance of IGF-1 for brain development is evident from transgenic animal studies showing that IGF-1 loss in the brain resulted in microcephaly and hypomyelination, while overexpression of IGF-1 led to increased brain volume." (PMID 37404461, 2023). "In humans, IGF-1 deficiency caused by homozygous mutations in the IGF1 causes microcephaly, mental retardation, deafness, and postnatal growth failure, confirming the essential role of IGF-1 as a neurotrophic factor." (PMID 35840554, 2022). "The presence of microcephaly is also associated with GHI defects such as IGF-1 and IGF-2 defects and IGFALS and IGF1R mutations." (PMID 35949366, 2022). "Reduced expression of IGF-1 has been reported to cause deafness, mental retardation, postnatal growth failure, and microcephaly." (PMID 35840554, 2022). "IGF-1 receptor (IGF1R) mutations are characterised by IGF-1 insensitivity causing impaired foetal and postnatal growth associated with high/normal IGF-1 levels and microcephaly/developmental delay." (PMID 33055295, 2020). "In 2010, a heterozygous frameshift mutation in IGF1 was associated with short stature and microcephaly in two siblings." (PMID 31939486, 2019). "Homozygous mutations of IGF-1 were found in a few patients presenting with severe pre- and post-natal growth failure, microcephaly and deafness." (PMID 30859796, 2019). "Deficiency of Igf1 and its receptor in mice is usually postnatally lethal and those mice that survive to adulthood show microcephaly associated with increased neuronal death and myelination impairment." (PMID 28963396, 2017). "Rare cases of IGF1 deficiency in humans are characterized by growth alteration, microcephaly, sensorineural deafness, and delayed psychomotor development." (PMID 28963396, 2017). "Individuals with homozygous mutations of the IGF1 gene exhibit microcephaly, mental retardation and bilateral sensorineural deafness." (PMID 27483352, 2016). "Deficiency in the IGF1 gene in humans is associated with neuronal disorders such as microcephaly, mental retardation and bilateral sensorineural deafness." (PMID 27483352, 2016). "Infant IGF-1 gene defects are associated with microcephaly and growth failure but cause-effect relationships among IGF-1 levels, growth failure and impaired brain development in preterm infants remains unknown." (PMID 37404461, 2023). "Furthermore, the smaller-sized pups showed a decrease in the mRNA expression levels of insulin-like growth factor (IGF)-1 and the expression levels of several microcephaly associated genes, when compared to their typical-sized siblings." (PMID 32498399, 2020). "Furthermore, in both genotypes, the downregulation of insulin-like growth factor (IGF)-1 and several microcephaly genes, along with neuronal loss, were detected in postmortem brain recovered from pups exposed to ZIKV." (PMID 32498399, 2020).
microcephaly (continued). "For patients with intrauterine growth retardation, possibly with microcephaly, and who have sporadic occurrence of psychomotor retardation and deafness, it may be worthwhile to look for mutations in IGF1; however, genotyping is somewhat ambiguous in these patients." (PMID 31555216, 2019). "Mutations or deletions of IGF1 are associated with microcephaly, sensorineural deafness, and mental retardation, a clinical picture consistent with the phenotype of IGF-I gene knockout mice characterized by small brains, hypomyelination, and loss of certain subtypes of neurons." (PMID 23060858, 2012). "The IGF pathway is essential for organismal development, and IGF1 knockout in mice leads to microcephaly." (PMID 40799188, 2025). "Homozygous mutations or deletions in IGF1 are rare, but can result in GHI with clinical features including birth of newborns small for gestational age and postnatal growth impairment, microcephaly with developmental delay, and hearing loss." (PMID 40868191, 2025). "Clinical manifestations can include skeletal abnormalities, microcephaly, elevated serum levels of GH, IGF-1, IGFBP-3 and ALS." (PMID 40868191, 2025). "Homozygous mutations in the IGF-1 gene lead to IGF-1 deficiency in humans, resulting in microcephaly, mental retardation, deafness, and postnatal growth failure." (PMID 38300646, 2024). "Global IGF-1 or its receptor (IGF-1R) deficiency typically leads to lethality, and in the case of survival, individuals present with microcephaly and suppressed somatic growth." (PMID 38247874, 2024). "Accordingly, the overexpression of IGF-1 in rodent brains resulted in brain enlargement, while the deletion of IGF-1 or conditional deletion of IGF1R expression in the brain led to microcephaly and hypomyelination." (PMID 36973010, 2023). "For example, the majority of CDG patients analyzed in the present study showed growth failure and microcephaly, which are also clinical hallmarks of IGF-1/IGF-1R defects." (PMID 35211808, 2022). "Median (IQR) circulating levels of IGF-1 were higher in patients with severe microcephaly (162 ng/mL vs 129 ng/mL [to convert to nanomoles per liter, multiply by 0.131]; P = .01), but levels of IGFBP3 were not statistically significantly different." (PMID 33983398, 2021). "Using a mice model with IGF-1 gene knockout, animals were presented with microcephaly and demyelination in the whole brain, whereas the overexpression of IGF-1 was shown to cause macrocephaly." (PMID 32498399, 2020). "Homozygous defects in IGF1 lead to pre and postnatal short stature, microcephaly and intellectual impairment (OMIM 608747)." (PMID 31939486, 2019). "Classically, patients with heterozygous defects in IGF1R present pre and postnatal growth retardation, microcephaly and IGF-1 levels above the mean for age and sex (OMIM 270450)." (PMID 31939486, 2019). "A reduced IGF-1 signaling, due to mutation of IGF-1 and its receptor gene, caused microcephaly and mental impairment." (PMID 29149058, 2017). "Other characteristic features that distinguish these cases include prenatal growth failure, microcephaly, and developmental delay with both IGF1 and IGF1R, sensorineural deafness with IGF1, and immunodeficiency with STAT5B." (PMID 24257104, 2013). "IGF-1 knockout mice show microcephaly and demyelination of the whole brain and overstimulation of IGF-1 leads to macrocephaly." (PMID 22778966, 2012). "Genetic defects in either IGF-1 or IGF-1R that result in SGA size typically correlate with phenotypical features such as microcephaly and mental retardation." (PMID 22587301, 2012). "Supporting this hypothesis, both probands, B.III.2 and B.III.3, were born SGA and had microcephaly, typical features of IGF1 resistance." (PMID 40150646, 2025).
microcephaly (continued). "Moreover, alterations in GH and IGF1 signaling are well-known to result in a decline in physical and mental function (neurogenesis, microcephaly, mental impairment, psychomotor and behavioral deficits, and hearing loss) in addition to >90% lethality." (PMID 34944082, 2021). "Interestingly, at the age of 27 months, patients in the group with severe microcephaly presented higher IGF-1 levels, although the levels were still within the reference range." (PMID 33983398, 2021). "Homozygous IGF1 defects that result in complete loss of functional IGF-I are associated with extreme growth failure, both pre-natal and post-natal, together with sensorineural deafness, microcephaly and mental retardation." (PMID 31555216, 2019). "Mutations of IGF-1 gene result in decreased serum levels or binding affinity of IGF-1; patients are characterized by severe intrauterine growth retardation, microcephaly, postnatal growth failure, severe psychomotor retardation, sensorineural deafness, and mild dysmorphic features." (PMID 30018981, 2018). "Alternatively, the low expression of IGF-1 detected in the postmortem brains of pups heterozygous for the Becn1 gene born to ZIKV-infected dams may have triggered neuronal loss and subsequently downregulated the microcephaly genes." (PMID 32498399, 2020).
non-small cell lung carcinoma (35 papers, 2009 to 2025). A group of at least three distinct histological types of lung cancer, including non-small cell squamous cell carcinoma, adenocarcinoma, and large cell carcinoma. "The insulin-like growth factor-1 (IGF-1) signaling pathway has been implicated in non-small cell lung cancer (NSCLC) outcomes and resistance to targeted therapies." (PMID 31393907, 2019). "A 3′UTR polymorphism in IGF1 predicts survival of Chinese non-small cell lung cancer patients." (PMID 27144430, 2016). "miR-135a promoted cell apoptosis and inhibited cell proliferation, migration, invasion, and tumor angiogenesis by targeting the IGF-1 gene through the IGF-1/PI3K/Akt signaling pathway in non-small cell lung cancer (NSCLC)." (PMID 34956857, 2021). "In non-small cell lung cancer, IGF-1 treatment of erlotinib-inhibited cells increased IGF1R/EGFR heterodimerization, leading to mTOR-mediated synthesis of EGFR and survivin, which counteracted the antiproliferative effects of Erlotinib." (PMID 30729097, 2019). "In addition, patients with non-small cell lung cancer (NSCLC) had higher IGF1 and lower IGFBP-3 and IGFBP-7 serum and tumor tissue concentrations compared to patients with noncancerous lung diseases." (PMID 31565100, 2019). "Insulin-like growth factor-1 (IGF-1) -induced epithelial-mesenchymal transition (EMT) plays a key role in the metastasis and drug resistance of non-small cell lung cancer (NSCLC)." (PMID 31413745, 2019). "Moreover, IGF-1/IGF-1R antibodies are well tolerated in clinical trials but fail to generate overall therapeutic advantages in patients with small cell lung cancer or in patients with non-small cell lung cancer by combination with chemotherapy or tyrosine kinase inhibitors (TKIs)." (PMID 30018981, 2018). "Given that IGF-1 truncation by DPP-IV affects the activation of IGF-1R, we next investigated the expression levels of DPP-IV in human non-small-cell lung cancer tissues with quantitative RT–PCR." (PMID 23675206, 2010). "in non-small cell lung cancer demonstrated that CAFs promote ANXA2 expression and phosphorylation via secretion of hepatocyte growth factor (HGF) and insulin-like growth factor 1 (IGF-1), activating c-MET and IGF-1R receptors, thereby enhancing the epithelial–mesenchymal transition (EMT) process." (PMID 40837013, 2025). "Furthermore, insulin-like growth factor-1 (IGF-1)-induced epithelial–mesenchymal transition (EMT) plays a key role in the metastasis and drug resistance of non-small-cell lung cancer." (PMID 33660008, 2021).
amyotrophic lateral sclerosis (33 papers, 2009 to 2025). Amyotrophic lateral sclerosis (ALS) is a neurodegenerative disease characterized by progressive muscular paralysis reflecting degeneration of motor neurons in the primary motor cortex, corticospinal tracts, brainstem and spinal cord. "IGF-1 expression counteracts muscle function decline in mouse models of muscular dystrophy and amyotrophic lateral sclerosis, activates satellite cells, and improves the survival of motor neurons." (PMID 23967261, 2013). "In a model of amyotrophic lateral sclerosis (ALS), a disease with loss of motor neurons and progressive muscle weakness, muscle overexpression of IGF-1 slowed the disease progression." (PMID 23125840, 2012). "The positive safety profile of IGF-1 treatment has also been established in other studies involving patients with amyotrophic lateral sclerosis (ALS)." (PMID 37242543, 2023). "Of the retrieved articles, we found nine articles about the effect of GH in healthy patients who suffered from traumatic brain injury (TBI), and six studies (four using IGF-1 and two GH therapy) in patients with amyotrophic lateral sclerosis (ALS)." (PMID 29149058, 2017). "In a model of amyotrophic lateral sclerosis (ALS), IGF-1 treatment, acting specifically through astrocytes, reduced neurotoxicity and rescued the disease-associated neurite retraction." (PMID 23847531, 2013). "In mouse and cell models of amyotrophic lateral sclerosis (ALS), IGF1 also strongly protects mitochondria from apoptosis and upregulates mitophagy, as evidenced by a decrease in the p62 level and an increase in the LC3-II level." (PMID 33816476, 2021). "In an animal model of amyotrophic lateral sclerosis (ALS), it was previously found that regulating the level of IGF-1 could reduce motor neuron death, delay the course of the disease, and delay the occurrence of muscle atrophy." (PMID 35573286, 2022). "Moreover, IGF-1 has been demonstrated to be beneficial in amyotrophic lateral sclerosis (ALS)." (PMID 35203722, 2022).
brain injury (33 papers, 2010 to 2025). Acute and chronic (see also brain INJURIES, CHRONIC) injuries to the brain, including the cerebral hemispheres, CEREBELLUM, and brain STEM. "Higher serum IGF-1 levels have been associated with better recovery of white matter and memory function in brain injury patients." (PMID 41041670, 2025). "Actually, administration of IGF-1 reduces the death of nerve cells in a model of ischemic brain injury." (PMID 38892790, 2024). "Overexpression of IGF-1 has been found to enhance dendritic ramification of immature hippocampal neurons in mice with traumatic brain injury and improve dendrite spinous density in adult Cdkl5−/y mice." (PMID 37638322, 2023). "IGF-1 has been recognized as a potent and wide-spectrum neuroprotective agent in all types of brain injuries." (PMID 35073748, 2022). "IGF-1 was thought to be a typical neuronal pro-survival factor in various brain injuries, promoting the clearance of Aβ and suppressing inflammatory responses." (PMID 36352898, 2022). "Here, we utilized a transgenic mouse model in which conditional overexpression of IGF1 by astrocytes results in increased hippocampal levels of IGF1 acutely after contusive brain injury." (PMID 32276671, 2020). "In this regard, the role of endogenous IGF-1 in brain responses to brain insults like excitotoxicity, a common pathology in brain injuries, remains to be elucidated." (PMID 31338023, 2019). "It seems also that poststroke serum IGF-1 levels are correlated with outcome from ischemic brain injury, with its higher levels reducing lethality." (PMID 26417600, 2015). "Following brain injury, IGF-1 expression changes both locally and in peripheral circulation." (PMID 41041670, 2025). "Brain injury triggers astrocyte activation and the synthesis of vital neurotrophic factors that promote neuronal growth and recovery, such as Insulin-like Growth Factor 1 (IGF-1) and Vascular Endothelial Growth Factor (VEGF)." (PMID 39451242, 2024). "Moreover, IGF-1 is under investigation as a potential treatment for improving neurological recovery after brain injury; however, randomised controlled trials are required in order to clarify its potential usefulness and safety for clinical use." (PMID 38539339, 2024). "In addition, the supplement treatment of IGF-1, which likely replaced the IGF-1 loss in old plasma, resulted in reduced acute brain injury in the aging ICH rats." (PMID 31040201, 2019). "Thus we tried to understand, through the literature, if there are grounds to identify the IGF-1 as a crucial marker in serum and CSF of those patients suffering from traumatic brain injuries." (PMID 26417600, 2015). "However, the roles of IGF-1 variants in mild traumatic brain injury (mTBI) are not yet fully understood." (PMID 31787098, 2019). "The researchers concluded that the pulsed magnetic field might increase the IGF-1 levels in the cerebrospinal fluid of brain injury patients, which may promote recovery of patients’ activities of daily living, suggesting its potential clinical value in treating brain injury." (PMID 38612456, 2024). "Preterms with brain injury presented similar levels of IGF-1 as preterm controls, but subanalysis showed a borderline decrease in IGF-1 levels on day 18 in cases of severe IVH." (PMID 37292373, 2023). "A study observing the effect of IGF-1 on the central nervous system showed that IGF-1 concentrations increase in the core and striatum of induced ischemic brain injury 48 h after MSC IV infusion." (PMID 35741711, 2022). "For example, insulin-like growth factor-1 (IGF-1) secreted by astrocytes supports the proliferation of oligodendrocytes and generation of myelinating oligodendrocytes under conditions of brain injury." (PMID 31920724, 2019). "Insulin-like growth factor 1 (IGF-1) is an important pleiotropic hormone that exerts neuroprotective and neuroreparative effects after a brain injury." (PMID 31787098, 2019).
brain injury (continued). "However, the IGF-1 method changed from a manual to an automated method during this study, and these findings have not been validated in a population that includes patients with mild, moderate, and severe traumatic brain injuries or sports-related concussion (SRC)." (PMID 29609574, 2018). "More specifically the ameliorative effect of IGF-1 could be primarily attributed to its effect in increasing food intake, the parameter shown to have the strongest improvement since inadequate nutrition is known to be a major clinical problem following brain trauma." (PMID 26417600, 2015). "Similar to BDNF, IGF-1 also plays an important role after brain injury and studies have shown that IGF-1 may mediate the exercise-induced regulation of BDNF and cognitive improvements after brain injury." (PMID 38397427, 2024). "Similarly, if EPO and IGF-1 levels in serum are not changed after brain injury, it would be rather impossible that systematically administration of them to be of value." (PMID 37292373, 2023).